CASP1 (caspase 1)
Diseases named in the same sentence as CASP1 in open-access papers (continued):
Sharing a sentence is not in itself a finding about the gene and the disease.
liver fibrosis (continued). "Conversely, the inhibition of caspase-1 and gasdermin D (GSDMD) can suppress pyroptosis and mitigate the progression of liver fibrosis." (PMID 40406118, 2025). "For example, a study demonstrated that the inhibition of pyroptosis by targeting caspase-1 or NOD (nucleotide-binding and oligomerization domain)-like receptor (NLR) protein 3 (NLRP3) significantly inhibits liver fibrosis or cirrhosis." (PMID 40667485, 2025). "Pyroptosis and hepatic fibrosis were induced by activating NOD-like receptor family pyrin domain containing 3 (NLRP3) inflammasomes in primary hepatocytes from mice, and blocking caspase-1 and GSDMD inhibited pyroptosis and hepatic fibrosis." (PMID 38086792, 2023). "Caspase-1 expression correlated with elastography-based liver fibrosis (r = 0.35, p = 0.02), whereas P2X7R, P2X4R, NRLP3, Caspase-1, and IL-2 expression correlated with circulating markers of disease severity." (PMID 35806450, 2022). "Gardenoside can ameliorate lipid deposition and liver fibrosis, and has been shown to decrease the expression levels of dipeptidyl peptidase-4 (DPP4), CCCTC-binding factor (CTCF), NLRP3, ASC, caspase-1 p20, GSDMD-N, and IL-1β in vitro and in vivo NAFLD models." (PMID 36016562, 2022). "Liver fibrosis levels were flagrantly higher (p<0.01), and TNF-α, NOD-like receptor protein 3 (NLRP3), caspase-1, interleukin-18 (IL-18), and interleukin-1β (IL-1β) protein or gene expression were manifestly up-regulated (p<0.01)." (PMID 35195182, 2022). "Masson and immunohistochemical staining revealed that, overexpression of Anxa2 aggravated liver fibrosis in NASH mice, and this pro-fibrotic effect was significantly reversed by the inhibition of Caspase-1." (PMID 36324154, 2022). "Considering the pathogenic importance of NLRP3 inflammasome-induced pyroptosis in liver fibrosis, we measured the levels of key markers for pyroptosis, including NLRP3, pro-caspase-1, cleaved Caspase-1, cleaved GSDMD-N, IL-1β, and IL-18." (PMID 34839365, 2021). "In fact, CASP1 is a component of the inflammasome complex NRLP3 which is involved in fibrotic and sclerotic liver diseases such as liver fibrosis, PSC and biliary obstruction." (PMID 31900160, 2020). "Ursolic acid inhibits KC pyroptosis in liver fibrosis in vitro and in vivo by suppressing the protein expression of pyroptosis-related indicators (NLRP3, pro-caspase-1, cleaved caspase-1, GSDMD, GSDMD-N, and IL-1β) in the NOX2/NLRP3 inflammasome signaling pathway." (PMID 40667485, 2025). "In vivo experiments have shown that it could reduce liver fat content, alleviate the expression of liver fibrosis indicators and autophagy, and inhibit the expression of NLRP3, ASC, caspase-1, and IL-1β." (PMID 36016562, 2022). "PA could also significantly up-regulate SOD and GSH-px levels (p<0.01), down-regulate IL-1β, IL-18, caspase-1, NLRP3, and TNF-α protein or gene expression in PBC mice (p<0.01) and inhibit liver fibrosis levels (p<0.01)." (PMID 35195182, 2022). "Accordingly, the absence of interleukin 1α or 1β (both targets of caspase-1) inhibits the evolution of liver steatosis to steatohepatitis and liver fibrosis." (PMID 28163820, 2017). "Consistently, our in vivo studies showed that inhibition of IL-1β level with caspase-1 inhibitor dramatically reduced MPO activity in the liver and ameliorated liver fibrosis in BDL mouse model, suggesting an important role of IL-1β in triggering tissue inflammation and fibrosis during cholestasis." (PMID 27924062, 2016). "We found that genetic deletion of Nlrp3 or Casp1, or pharmacologic inhibition of Nlrp3 using an oral inhibitor (MCC950) did not ameliorate the development of any of the histological features of fibrosing steatohepatitis (hepatic fibrosis, inflammation, or steatosis) in HFHC-fed mice." (PMID 36641116, 2023).
liver fibrosis (continued). "Previously, it was reported that upstream blockade of IL-1β maturation by NLRP3 inflammasome and caspase-1 inhibition reduced hepatic fibrosis, proving that lacking IL-1β in NASH may ameliorate pro-fibrotic events." (PMID 36611037, 2023). "Moreover, Anakinra treatment alleviated liver injury and inflammation without affecting fibrosis in a mouse model of CCl4-induced liver fibrosis, as shown by a decrease in caspase-1 and IL-1β with unchanged CTGF and TIMP expression." (PMID 35707547, 2022). "Finally, to verify the in vivo significance of our hypothesis, Casp-1, ASC, NLRP3, and AIM2 KO mice and WT mice, as control, were infected with B. abortus, and 4 weeks later, animals were sacrificed to determine the role of inflammasome in the liver fibrosis." (PMID 32038610, 2019).
psoriasis (37 papers, 2013 to 2025). An autoimmune condition characterized by red, well-delineated plaques with silvery scales that are usually on the extensor surfaces and scalp. "In psoriasis, caspase-1 is active in epidermal keratinocytes and has been linked to IL-1β production via ASC-dependent inflammasome complexes, such as NLRP3 and AIM2." (PMID 28422993, 2017). "During IMQ-induced skin inflammation, the expression of AIM2 inflammasome components, such as AIM2, ASC, and pro-caspase-1, in skin lesions is upregulated, and serum levels of IL-17A, a cytokine which has been implicated in the pathogenesis of psoriasis, are increased." (PMID 36982727, 2023). "The increased levels of caspase-1 and multiple proinflammatory cytokines such as IL-1β and TNF-α have been linked to the development of psoriasis, suggesting that caspase-1 might be a crucial target for the treatment." (PMID 34654807, 2021). "However, Cho found that the NLRP3 inflammasome can be activated in IMQ-treated caspase-1-deficient mice, although the severity of psoriasis was much lower than in wild-type mice." (PMID 32528469, 2020). "So far, caspase-1 has been identified active and linked to IL-1β maturation in psoriasis." (PMID 28422993, 2017). "Mutations in genes encoding proteins involved in this regulation might contribute to lower the cytosolic DNA detection threshold required for caspase-1 activation possibly leading to auto-inflammatory syndromes such as psoriasis, which is associated with AIM2 inflammasome activation." (PMID 23630667, 2013). "Western blot analysis showed that psoriasis-derived MDMs had elevated expression of pyroptosis-related proteins, Caspase 1 and Caspase 4, when compared to healthy controls." (PMID 40722833, 2025). "In this study, we provide a comprehensive analysis of pyroptosis-related genes (PRGs) in psoriasis, identifying key molecular players such as CASP1, CASP5, AIM2, NOD2, and IL1B that drive the inflammatory response and disease progression." (PMID 40771724, 2025). "In vitro experiments confirmed that MDMs derived from psoriasis patients overexpressed pyroptosis-related molecules (Caspase 1 and Caspase 4) as well as pro-inflammatory cytokines (TNFα, IL6, IL1β) when compared to healthy controls." (PMID 40722833, 2025). "Upon activation, both AIM2 and NOD2 trigger the formation of inflammasomes that ultimately lead to CASP1 activation, which processes pro-inflammatory cytokines such as IL-1β, which is also a key player in psoriasis through our former analysis." (PMID 40771724, 2025). "Our findings underscore the critical role of pyroptosis in psoriasis pathogenesis and demonstrate that targeting CASP1 and CASP5 through CRISPR-Cas9 gene editing can effectively alleviate disease symptoms and reduce inflammation in the IMQ-induced mouse model." (PMID 40771724, 2025). "CASP1 has long been recognized as a central mediator of IL-1β and IL-18 processing, two cytokines that contribute to the chronic inflammation in psoriasis." (PMID 40771724, 2025). "While our study provides compelling evidence for the role of pyroptosis in psoriasis and the potential of CASP1 and CASP5 as therapeutic targets, several questions remain to be addressed." (PMID 40771724, 2025). "In previous studies, elevated expression of AIM2 and Caspase-1 has been observed in rheumatoid arthritis, systemic lupus erythematosus, Sjogren’s syndrome, and psoriasis." (PMID 39100670, 2024). "VX765 is a specific caspase-1 inhibitor that has been approved by the FDA to be used in clinical trials of adult patients with psoriasis (ClinicalTrials.gov Identifier: NCT00205465) and epilepsy (ClinicalTrials.gov Identifier: NCT01048255 and NCT01501383)." (PMID 39768185, 2024). "In psoriasis, a chronic inflammatory skin disease, IL-1β and IL-18 are increased, and excessive NLRP3 and caspase-1 expression levels are associated with its development." (PMID 39684233, 2024).
psoriasis (continued). "We verified the absence of GSDMD in the skin of Gsdmd-/- mice by western blotting and found that after induction of psoriasis in Gsdmd-/- mice, the expression and activation of caspase 1, an upstream molecule of pyroptosis, were decreased." (PMID 39717896, 2024). "We demonstrated that AIM2 functions through its canonical activation pathway involving ASC and caspase-1 inducing the generation of the IL-23/IL-17 immune axis required for developing psoriasis." (PMID 39352743, 2024). "We found that genetic ablations of PYCARD or caspase-1 prevented the development of IMQ-induced psoriasis, highlighting a role in the inflammasome." (PMID 39352743, 2024). "In psoriasis, pathogenic T cells activate the NLRP3 inflammasome in keratinocytes, leading to the cleavage of pro-IL-1β by caspase-1 and the production of active IL-1β, which exacerbates skin inflammation." (PMID 38892253, 2024). "In a mouse model of psoriasis induced by imiquimod, the extract reduces psoriasis-related inflammation, including caspase-1 activation, IL-1β maturation, IL-17 production, and overall disease severity." (PMID 37836436, 2023). "Whereas most research focused on one or two PRGs in vivo or vitro, for instance, the pathogenesis of psoriasis is closely related to caspase-1, IL-1β, IL-18, or GSDMD." (PMID 36110207, 2022). "We found that PUN can relieve psoriasis-like symptoms by suppressing the nuclear factor kappa B (NF-κB)-mediated IL-1β transcription and caspase-1-regulated IL-1β secretion in vivo and in vitro." (PMID 35153790, 2022). "In contrast, psoriasis skin-derived S.B cells expressed high levels of pyroptosis-related genes, such as CASP1, CAPS8, GSDMA, GSDMB, and GSDMD." (PMID 35962439, 2022). "Another caspase-1 inhibitor Ac-YVAD-CMK was shown to attenuate the imiquimod-induced psoriasis-like phenotype in a mouse model." (PMID 34654807, 2021). "Activation of proinflammatory caspase-1 and caspase-11 in immune cells is sufficient to induce a psoriasis-like phenotype; however, in a psoriasis mouse model, these caspases are dispensable for inflammasome activation in keratinocytes/fibroblasts." (PMID 32528469, 2020). "We found that the interaction of CASP10 - CASP1, CASP10- CASP3, CASP10- CASP4, CASP10- CASP9, CASP10- CASP12, CASP8 - CASP3, CASP8 - CASP4, and CASP1 - CASP12 is important for the risk of psoriasis." (PMID 30906769, 2019). "Among the investigated key cytokines relevant in psoriasis, IFNγ was detected as the main inducing factor for inflammatory caspase-5 besides caspase-1 in keratinocytes, whereas IL-17A had an amplifying effect." (PMID 28422993, 2017). "This analysis revealed that both STAT3 and Caspase-1 are significantly upregulated in psoriasis." (PMID 40405066, 2025). "Previous studies have indicated that pyroptosis in psoriasis triggers caspase-1 activation, increases IL-1β and IL-18 expression, and activates the IL-23/Th17 pathway, leading to the secretion of large amounts of inflammatory cytokines and chemokines, which ultimately induces skin inflammation." (PMID 40722833, 2025). "Additionally, topical application of Cornus officinalis seed extract inhibited the cleavage of the inflammasome activation marker caspase-1, alleviating psoriasis-like symptoms like desquamation, erythema, epidermal thickening." (PMID 41383588, 2025). "Consistent with earlier research, our study found that the expression of GSDMD and its upstream molecule caspase 1 was upregulated in the skin of psoriasis patients and psoriasis-like mice, indicating that the pyroptosis pathway is activated in psoriasis skin lesions." (PMID 39717896, 2024). "Psoriasis is an autoimmune disease with high caspase-1 activity in psoriatic epidermis." (PMID 39689159, 2024). "First, we observed a significant increase in the expression of PYCARD (encoding for ASC) and CASP1 (encoding for caspase-1) in the injured skin of patients with psoriasis compared with nonlesioned or healthy control skin groups." (PMID 39352743, 2024).
psoriasis (continued). "Additionally, we identified 10 key genes including AIM2, BAK1 and CASP1, and confirmed the accuracy of these key genes in diagnosing psoriasis." (PMID 37861483, 2023). "We firstly found that the IMQ-induced psoriasis-related female mice showed depressive- and anxiety-like behaviors, which were associated with microglial activation, the up-regulation of NLRP3, Caspase-1, IL-18, and IL-1β, and the down-regulation of CRMP2 and α-tubulin." (PMID 36138986, 2022). "Similarly, in human studies, skin sections of psoriasis patients showed elevated levels of IL-18 and Caspase-1 compared to healthy subjects." (PMID 36032110, 2022). "VX-765 is a caspase-1 inhibitor used to treat chronic epilepsy and psoriasis." (PMID 26709961, 2015). "Notably, GZMB and CASP1 occupied central positions within the network, each displaying multiple direct links with other PRGs, suggesting potential roles as core regulators of pyroptotic signaling in psoriasis." (PMID 40771724, 2025). "Taken together, our findings indicate that PUN can relieve psoriasis by repressing NF-κB-mediated IL-1β transcription and caspase-1-regulated IL-1β secretion, which provide evidence that PUN might represent a novel and promising candidate for the treatment of psoriasis." (PMID 35153790, 2022). "Building on these insights, we sought to test the therapeutic potential of targeting key pyroptosis-related genes, specifically CASP1 and CASP5, in the treatment of psoriasis." (PMID 40771724, 2025). "We employed CRISPR-Cas9 gene editing, delivered via lipid nanoparticles (LNPs), to selectively knock out Casp1 and Casp11 (murine homolog of human CASP5) in keratinocytes within the IMQ-induced psoriasis mouse model." (PMID 40771724, 2025). "To explore the therapeutic potential of targeting these hub genes in alleviating psoriasis, we used Lipid Nanoparticles (LNPs) to deliver gRNAs targeting Casp1 and Casp5 to keratinocytes in the IMQ-induced psoriasis mouse model." (PMID 40771724, 2025). "Our analysis identified CASP1, CASP5, AIM2, NOD2, GZMB, GZMA, and IL1B as key hub genes in the inflammatory pathways driving psoriasis pathogenesis." (PMID 40771724, 2025). "Caspase-1, or CASP1, is a central component of pyroptosis and is crucial in regulating apoptosis and inflammatory responses, with its activity elevated during psoriasis pathogenesis." (PMID 40405066, 2025). "A strong upregulation of Casp1 and Il1b expression was also found in the IMQ-induced psoriasis mouse model." (PMID 39352743, 2024). "In an IMQ-induced psoriasis mouse model, D3T treatment notably reduced ear thickness, skin redness, scaling, and the expression of KI-67, the NLRP3 inflammasome, and cleaved caspase-1 in skin samples." (PMID 38892253, 2024). "One study revealed that inflammasome sensors, NLRP3, NLRP1, CASP1, and AIM2, enhanced expression in psoriasis patients." (PMID 36110207, 2022). "Given this critical role of CASP1 in amplifying inflammation, and the fact that CASP5 is similarly involved in downstream pyroptotic signaling, targeting CASP1 and CASP5 emerges as the most effective strategy to mitigate the inflammatory response in psoriasis." (PMID 40771724, 2025). "The gene expression of these key members (Caspase-1, Nlrp3, Gsdmd, Il-1β) was significantly increased in the lesions of psoriasis (P < 0.01) compared with nonlesional skin." (PMID 38125299, 2024). "In the present study, we demonstrated that IMQ-induced psoriasis could induce NLRP3 and caspase-1 expression and be downregulated through D3T treatment." (PMID 37686332, 2023). "IL-18 levels are usually elevated in psoriasis, systemic lupus erythematosus (SLE), hypertension, chronic kidney disease, multiple sclerosis (MS) patients and Coronavirus disease 2019 (COVID-19) which correlates with caspase-1 levels." (PMID 36032110, 2022). "In addition, we found higher NLRP3, ASC, caspase-1 and IL1B mRNA levels in PBMCs from psoriasis patients compared with healthy individuals." (PMID 36293012, 2022).
psoriasis (continued). "In addition, we found that the overall expression of NLRP3, ASC, IL-1β and caspase-1 is higher in the peripheral blood of psoriatic patients compared to normal controls, implying that overactivation of the NLRP3 inflammasome may also contribute to psoriasis-associated inflammatory responses." (PMID 36293012, 2022). "The immunohistochemical results showed that the NLRP3 inflammasome signals were observed to be significantly increased in the psoriasis mice; furthermore, the expressions of NLRP3, ASC, caspase-1, and IL-1β were upregulated, which were all inhibited through EPD treatment." (PMID 31181689, 2019). "These preliminary docking results suggested that PSVII exhibited a strong binding affinity for the Caspase-1 and STAT3 proteins, indicating that STAT3, Caspase-1, and pyroptosis could be key targets and mechanisms for PSVII’s therapeutic intervention in psoriasis." (PMID 40405066, 2025). "Notably, CASP1 and CASP5 were highlighted as central downstream effectors of pyroptosis, making them attractive therapeutic targets for modulating skin inflammation and hyperplasia in psoriasis." (PMID 40771724, 2025). "Additionally, we targeted CASP1 and CASP5 using CRISPR-Cas9 delivery via lipid nanoparticles (LNPs) to selectively knock out these genes in keratinocytes, resulting in significant therapeutic effects in the IMQ-induced psoriasis mouse model." (PMID 40771724, 2025). "Notably, genes such as Nlrp3, Casp1, Casp4, IL-1β, IL-18, and Stat1 had high degree values, indicative of their significant position in the PPI network and potential targets for FZHFZY treatment of psoriasis." (PMID 41383588, 2025). "Furthermore, mRNA of NLRP1, NLRP3, AIM2, PYCARD and CASP1 was observed in both lesional and non-lesional epidermis of psoriasis patients." (PMID 37325658, 2023). "In contrast, methotrexate, a folate antagonist used for the treatment of severe inflammatory conditions, including psoriasis, did not reduce caspase-1 activity in psoriasis patients, suggesting that TNF-α inhibition is superior in reducing NLRP3-dependent inflammation during psoriasis." (PMID 37443800, 2023). "In psoriasis biopsy, the expression of NLRP3, caspase-1, and IL-1β was significantly upregulated compared to non-lesional psoriatic skin." (PMID 34707607, 2021).